PIM1 (Pim-1 proto-oncogene, serine/threonine kinase)
Diseases named in the same sentence as PIM1 in open-access papers (continued):
Sharing a sentence is not in itself a finding about the gene and the disease.
prostate carcinoma (continued). "Here, we performed a direct, unbiased chemical genetic screen to identify PIM1 substrates in prostate cancer cells." (PMID 33398037, 2021). "We anticipate that the characterization of additional PIM1 substrates will lend further mechanistic insights into the oncogenic properties imparted by PIM1 in prostate cancer." (PMID 33398037, 2021). "Results from our study further implicate PIM-1 as a key molecule involved in therapeutic resistance to AR and AKT inhibition and provide additional evidence to warrant further investigation of PIM-1 in prostate cancer." (PMID 34439133, 2021). "The authors conclude that PIM1 phosphorylation of these substrates regulates the AR transcriptome in prostate cancer cells." (PMID 34697370, 2021). "This suggests that PIM1-mediated phosphorylation of NDRG1 inhibits its ability to exert metastasis-suppressive functions in prostate cancer." (PMID 33398037, 2021). "We and others have previously shown that PIM1 phosphorylates AR, the primary therapeutic target in prostate cancer, at S213, affecting the expression of select AR target genes." (PMID 34697370, 2021). "PIM1 is expressed in the spleen, thymus, bone marrow, prostate, and oral epithelial and is found to be highly expressed in prostate cancer and other human malignancies." (PMID 34679086, 2021). "We have previously shown that PIM1 phosphorylates the androgen receptor (AR), the primary therapeutic target in prostate cancer, at serine 213 (pS213), which alters expression of select AR target genes." (PMID 34697370, 2021). "We have identified capping proteins CAPZA1 and CAPZB2 as PIM1 substrates, and shown that phosphorylation of either of them leads to increased adhesion and migration of human prostate cancer cells." (PMID 32771000, 2020). "In prostate cancer, miR-144 was shown to enhance radiotherapy sensitivity and suppress hypoxia-induced autophagy by inhibiting PIM1 expression." (PMID 32351538, 2020). "Our data indicate that PIM-1 overexpression in CTCs should be prospectively evaluated as a potential biomarker for prostate cancer management in a large and well-defined patient cohort." (PMID 32397108, 2020). "PIM1 is a kinase that is overexpressed in prostate cancer, while the two isoforms, PIM-1S and PIM-1L, are the major mediators of AR serine 213 (Ser-213) and threonine 850 (Thr-850) phosphorylation." (PMID 32397108, 2020). "We have shown that phosphorylation of the alpha 1 and beta 2 subunits by PIM1 reduces the actin capping activity of the CP heterodimer, resulting in increased prostate cancer cell motility." (PMID 32771000, 2020). "In prostate cancer, elevated PIM1 contributes to androgen deprivation therapy resistance reversed by a combination with PIM‐i." (PMID 32146726, 2020). "We report for the first time that PIM-1 is overexpressed in circulating tumor cells (CTCs) from metastatic castration-resistant prostate cancer patients (mCRPC)." (PMID 32397108, 2020). "PIM-1 has been shown to be overexpressed in approximately 50% of human prostate cancer specimens using tissue microarrays." (PMID 32397108, 2020). "In the last few years, an important body of work has demonstrated that PIM1 is an important partner of MYC function in prostate cancer and TNBC." (PMID 31570853, 2020). "According to data from the Betastasis database, both CAPZA1 and CAPZB mRNA levels positively correlated with PIM1 in primary prostate cancer patient samples." (PMID 32771000, 2020). "In contrast, miR-486 inhibits cell proliferation and invasion through repressing GAB2, PIK3R1, Snail, neuropilin-2, CDK4, or PIM-1 in non-small-cell lung cancer, colorectal cancer, prostate cancer, hepatocellular carcinoma, and breast cancer cells." (PMID 32155804, 2020). "It inhibited cancer progression in human prostate cancer PC3 cells by inhibiting PIM1 and disrupting the PIM1/CXCR4 interaction." (PMID 31100782, 2019).
prostate carcinoma (continued). "In prostate cancer, overexpression of either PIM1 or PIM3 positively correlates with tumor size, aggressiveness and/or poor patient survival." (PMID 31730483, 2019). "Myricetin exerts selective cytotoxic, pro-apoptotic, and anti-metastatic effects on prostate cancer cells by inhibiting PIM1 and disrupting the PIM1/CXCR4 interactions." (PMID 31170907, 2019). "Our data prompted us to examine clinical prostate cancer samples for their expression levels of PIM1, NFATC1 and/or ITGA5 mRNAs." (PMID 31730483, 2019). "These include the ITGA5 integrin, which is differentially expressed in the presence of wild-type versus phosphorylation-deficient NFATC1, and which is coexpressed with PIM1 and NFATC1 in clinical prostate cancer specimens." (PMID 31730483, 2019). "MiR-122 and miR-144 target PIM1 to inhibit cell autophagy and enhance radiosensitivity in prostate cancer cells." (PMID 29459645, 2018). "Conversely, by acting as a suppressor, PIM1 is frequently downregulated in other human malignancies, such as prostate cancer, pancreatic ductal carcinoma and non-small-cell lung cancer; in these cases, PIM1 expression is correlated with a good prognosis." (PMID 29472550, 2018). "Consistent with the findings in solid tumor, PIM-1 mRNA expression is also up-regulated during malignant transformation in prostate cancer and esophageal squamous cell carcinoma." (PMID 28851457, 2017). "In the development of prostate cancer, overexpression of PIM-1 drives normal duct epithelium toward PIN lesions." (PMID 28212321, 2017). "The Pim1 protein kinase plays an important role in the initiation and progression of human prostate cancer and is elevated in both epithelial and stromal tumor cells." (PMID 26956053, 2016). "MiR‐124 or miR‐144 overexpression can inhibit hypoxia‐induced autophagy and enhance radiosensitivity at least via downregulating PIM1 in prostate cancer cells." (PMID 26990493, 2016). "PIM1 has been identified as an important player in the control of cell growth and survival in hematopoietic, colon and prostate cancers." (PMID 26993775, 2016). "In this study, we found that miR‐124 and miR‐144 are two hypoxia‐responsive miRNAs, which can reduce hypoxia‐induced autophagy and enhance radiosensitivity of prostate cancer cells via reducing PIM1." (PMID 26990493, 2016). "Since we confirmed the regulative effect of miR‐124 and miR‐144 on PIM1, we then investigated their functional role in hypoxia‐induced autophagy and radiosensitivity of prostate cancer cells." (PMID 26990493, 2016). "By performing prediction using TargetScan 6.3, we observed that miR‐124 and miR‐144 are both potential regulators of PIM1, a well‐recognized oncogene of prostate cancer." (PMID 26990493, 2016). "In support of this notion, Siu and colleagues previously demonstrated in prostate cancer models that PIM-1 inhibition upregulates MIG6, a negative regulator of EGFR signaling, thereby inhibiting EGFR/MAPK activation." (PMID 27472392, 2016). "In contrast, knockdown of endogenous PIM1 reduced autophagy induced by hypoxia and sensitized prostate cancer cells to irradiation." (PMID 26990493, 2016). "Here we show that PC-3 prostate cancer cells overexpressing either Pim-1 or Pim-3 kinases form larger xenograft tumors than the parental PC-3 cells." (PMID 26075720, 2015). "We show here that tumorigenic growth of both subcutaneously and orthotopically inoculated prostate cancer xenografts is enhanced by stable overexpression of either Pim-1 or Pim-3." (PMID 26075720, 2015). "The utility of specific PIM1 inhibitors or monoclonal antibodies to treat cancer cells has been documented in prostate cancer and leukemia." (PMID 25834102, 2015). "Treatment with the c-Myc inhibitor 10058-F4 reduced Pim-1 protein and suppressed the tumorigenicity of the prostate cancer cells." (PMID 25491234, 2014).
prostate carcinoma (continued). "Elevated levels of Pim-1 have been found in human hematological malignancies and certain solid cancers, including prostate cancer, head and neck squamous cell carcinomas, colon carcinoma, and pancreatic ductal adenocarcinoma." (PMID 25342548, 2014). "The oncogenic serine/threonine kinase Pim-1 is upregulated in a number of human cancers including lymphomas, gastric, colorectal and prostate carcinomas." (PMID 25121590, 2014). "Previous reports have shown that PIM1 overexpression increased ERK1/2 phosphorylation in prostate cancer cells, increased p38-MAPK activation by phosphorylation in Basophils, and increased activation of JNK in cardiomyocytes by PIM3." (PMID 25238262, 2014). "The oncogenic role of Pim-1 and its cooperation with c-Myc have also been studied in prostatic cancer." (PMID 25491234, 2014). "To explore the role of Pim1 in prostate cancer, we generated conditional Pim1 transgenic mice, expressed Pim1 in prostate epithelium, and analyzed the contribution of PIM1 to neoplastic initiation and progression." (PMID 23565217, 2013). "This phenomenon has also been shown in human prostate cancer, in which PIM1 is most likely to collaborate with MYC in cellular transformation as it is the most consistently expressed gene among MYC-positive and MYC-negative prostate cancer tumor samples." (PMID 23565217, 2013). "Recently, Pim1 was found to be increased in solid tumors, including pancreatic and prostate cancers, squamous cell carcinoma, gastric, colorectal and liver carcinomas, and liposarcoma." (PMID 23565217, 2013). "The proto-oncogene HMGA1 encodes a chromatin “architectural transcription factor” that, evidence indicates, acts downstream of PIM1 in an HMGA1-mediated prostate cancer induction pathway." (PMID 22912571, 2012). "Lastly, the serine-threonine protein kinase gene PIM1, or Pim-1 oncogene, is found at increased levels within prostate cancer tissue." (PMID 23060898, 2012). "Both c-MYC and HMGA1 have also been found to be over-expressed in prostate cancers, suggesting the importance of the PIM1/c-MYC/HMGA1 signaling cascade in prostate carcinogenesis." (PMID 22912571, 2012). "PIM-1 and PIM-2 over expression in prostate cancer correlates with tumour progression and over expression of exogenous PIM-1 or PIM-2 in prostate cancer cell lines increases cell proliferation." (PMID 22193779, 2011). "PIM1 was of immediate interest because it is supposed to play an oncogenic role in several types of tumours, including prostate cancer." (PMID 22140532, 2011). "We then found a significant (p<0.01) correlation between ERG expression and PIM1 up-regulation in a prostate cancer dataset, further confirming the link between ERG and PIM1 in prostate cancer." (PMID 22140532, 2011). "This discovery provides novel insights into the role of TMPRSS2/ERG in prostate cancer progression and describes a new mechanism for PIM1 regulation mediated by the ERG DNA binding domain." (PMID 22140532, 2011). "Although there is little or no PIM1 expression in the benign prostatic epithelium, there is significant PIM1 expression in advanced cases of prostate cancer." (PMID 24213111, 2011). "To investigate the link between tERG and PIM1 in prostate cancer, we modulated ERG expression in the non malignant RWPE-1 prostate cell line." (PMID 22140532, 2011). "Among the genes significantly affected by all three ERG fusions, we noted the up-regulation of PIM1, an oncogene whose expression is increased in tumors from both haematological and epithelial origin, including prostate cancer." (PMID 22140532, 2011). "In human prostate cancer, PIM1 expression is known to be elevated in ~50% of human prostate cancer specimens and its cooperation with MYC was also proposed." (PMID 20515470, 2010). "The Pim-1 siRNA using in our experiments has been previously shown to specific knockdown Pim-1 in multiple prostate cancer cell lines." (PMID 21143989, 2010).
prostate carcinoma (continued). "The c-MYC inhibitor 10058-F4 suppressed the tumorigenicity of Pim1-expressing prostate cancer cells." (PMID 20515470, 2010). "Several inhibitors of Pim-1 have been shown to inhibit the growth of cancer cells, such as leukemic cells as well as prostate cancer cells." (PMID 21143989, 2010). "Pim-1 is overexpressed in several types of cancer, including lymphoid and haematopoietic malignancies, prostate cancer, squamous cell carcinomas, gastric carcinoma and colorectal carcinomas." (PMID 21143989, 2010). "One study used PC3 human prostate carcinoma cells to show that Pim1 overexpression accelerates tumorigenicity in these cells associated with elevated levels of c-MYC and the phosphorylation of proteins involved in protein synthesis." (PMID 20515470, 2010). "Interestingly in this regard, coexpression of Pim-1 and c-Myc in human prostate tumors has recently been associated with higher Gleason grades than overexpression of either one alone, suggesting that these oncoproteins synergize to induce advanced prostate carcinoma." (PMID 20958956, 2010). "Prostate cancer induced by mouse prostate-specific overexpression of c-MYC oncogene demonstrated Pim1 mRNA upregulation, suggesting possible synergistic effect between two oncogenes." (PMID 20515470, 2010). "One study used, PC3, an aggressive androgen-independent human prostate cancer cell line, to examine in vivo tumorigenicity of Pim1." (PMID 20515470, 2010). "Pim-1 also appears to be important in the development of human cancers, as the Pim-1 gene maps to an area showing karyotypic abnormalities in leukaemia, and the mRNA for Pim-1 has been shown to be up-regulated in prostate cancer and leukaemia." (PMID 16403219, 2006). "PIM1 promotes tumor growth in prostate cancer by interacting with MYC." (PMID 40018406, 2025). "Indeed, Pim1 has been shown to regulate the migration, proliferation and survival of prostate cancer cells." (PMID 40164682, 2025). "Additionally, PIM1 was found to be a senescence regulator, an epigenetic dynamics regulator, and a biomarker for prostate cancer." (PMID 40649898, 2025). "Thus, we designed experiments to test the importance of PIM1-induced LD accumulation for prostate cancer cell proliferation." (PMID 38097734, 2024). "We speculated that prostate cancer cells might accumulate and utilize LDs following PIM1 induction to promote survival under nutrient stress." (PMID 38097734, 2024). "Notably, LD accumulation downstream of PIM1 provides a significant survival advantage for prostate cancer cells during nutrient stress, such as glucose depletion." (PMID 38097734, 2024). "Despite an overall reduction, we speculated that specific alterations within the TG lipid class could still positively influence prostate cancer cell proliferation and survival following PIM1 induction." (PMID 38097734, 2024). "Moreover, blocking PPARα signaling using a specific inhibitor, GW6471, was sufficient to reduce LD accumulation and abrogate the effects of PIM1 induction prostate cancer proliferation." (PMID 38097734, 2024). "Our data show that PIM1 induction alters lipid composition in prostate cancer cells." (PMID 38097734, 2024). "Because PIM kinases are associated with tumor aggressiveness across a wide spectrum of solid tumors, we speculated that PIM1 could influence LD accumulation in prostate cancer." (PMID 38097734, 2024). "Altogether, these data demonstrate that PIM1 promotes LD accumulation in prostate cancer." (PMID 38097734, 2024). "The prevalence of PIM-1 kinase in these cancers, coupled with its crucial role in disease progression, underscores the importance of targeting PIM-1 for therapeutic interventions in prostate cancer and potentially other hematological malignancies where its expression is dysregulated." (PMID 39434908, 2024). "In the present study, upregulation of PPARα signaling contributed to LD accumulation following PIM1 induction, which may promote proliferation of prostate cancer cells." (PMID 38097734, 2024).
prostate carcinoma (continued). "Furthermore, the pro-survival effect of PIM1 on prostate cancer cells under nutrient stress was visible within 4 h and maintained through 71 h." (PMID 38097734, 2024). "Thus, further studies are warranted to target PIM1 and/or block LD utilization to increase prostate cancer sensitivity to treatments and overcome resistance." (PMID 38097734, 2024). "Moreover, PIM-1 overexpression combined with Myc leads to the development of the advanced form of prostate carcinoma." (PMID 37514177, 2023). "For example, in PC3-LN4 prostate cancer cells, intrinsic resistance to both allosteric and ATP-competitive AKTis has been demonstrated to involve AKTi-induced PIM1 upregulation followed by a PIM1-dependent increase in receptor tyrosine kinase expression via cap-independent translation." (PMID 35440108, 2022). "Similarly, in prostate carcinoma cell lines it has been shown that the increased sensitivity to radiotherapy mediated by miR-124 and miR-144 was a consequence of PIM-1 downregulation." (PMID 34993612, 2022). "In prostate cancer, PIM1 has been shown to play a role in metastases through a number of pathways, including (i) the activation of NFATC1, c-Myc, and Smad signaling, (ii) the inhibition of GSK3β and FOXP3, (iii) the upregulation of PTGS2, and (iv) altering integrin-dependent cell adhesion." (PMID 35892829, 2022). "PIM1, proviral insertion site in murine leukemia virus (PIM) kinase 1, belongs to the PIM kinase family and has been implicated in the control of cancer cell proliferation, migration, and apoptosis, particularly in prostate cancer and leukemia." (PMID 35186733, 2022). "Previous studies have shown that PIM is able to reactivate signaling cascades downstream of Akt to promote translation and suppress apoptosis and PIM1 increased expression of RTKs in prostate cancer patients in a cap-independent manner via control of internal ribosome entry." (PMID 33946744, 2021). "The PIM1 overexpression in prostate cancer has been found to decrease the patients’ survival." (PMID 34679086, 2021). "Thus, identifying direct substrates has allowed for the characterization of the mechanism by which PIM1 mediates an oncogenic phenotype—namely cell migration and invasion—in the context of prostate cancer." (PMID 33398037, 2021). "Still, the mechanism by which PIM1 promotes prostate cancer is not fully understood." (PMID 33398037, 2021). "PIM1 is a serine/threonine kinase upregulated in prostate cancer." (PMID 34697370, 2021). "The oncogenic potential of Pim1 was most extensively investigated in prostate cancer." (PMID 34267653, 2021). "Our study identifies new PIM1 substrates in prostate cancer cells in a direct, unbiased manner." (PMID 33398037, 2021). "PIM1 is a serine/threonine kinase over-expressed in prostate cancer." (PMID 34697370, 2021). "We used an unbiased method to identify direct PIM1 substrates in prostate cancer cells." (PMID 33398037, 2021). "We next tested whether the PIM1 dependence of these genes’ expression identified in LNCaP cells extends to other prostate cancer cell lines." (PMID 34697370, 2021). "In addition, our approach represents a direct method for identifying PIM1 substrates in prostate cancer cells." (PMID 33398037, 2021). "Moreover, PIM-1 overexpression was observed in high-grade prostate intraepithelial neoplasia and in prostate cancer compared to normal prostatic tissue and benign prostate hyperplasia." (PMID 32397108, 2020). "Moreover, PIM-1 is also upregulated in advanced prostate cancer and esophageal squamous cell carcinoma." (PMID 28851457, 2017). "Likewise CK2α, PIM1 is overexpressed in prostate cancer, leukemia and lymphomas and promotes oncogenesis by phosphorylation of BAD and collaboration with MYC23." (PMID 29042609, 2017). "PIM1 expression is usually upregulated in prostate cancer, which could be a result of activation of the JAK/STAT pathway." (PMID 26990493, 2016).